JPT2 (Jupiter microtubule associated homolog 2)
Description:
Nicotinic acid adenine dinucleotide phosphate (NAADP) binding protein required for NAADP-evoked intracellular calcium release. Confers NAADP-sensitivity to the two pore channels (TPCs) complex. Enables NAADP to activate Ca(2+) release from the endoplasmic reticulum through ryanodine receptors. (Microbial infection) Involved in the endolysosomal trafficking of human coronavirus SARS-CoV-2.
Synonyms: C16orf34; HN1L; L11; FLJ13092; KIAA1426
Tractability: Antibody: its Gene Ontology location is reachable by antibodies, with high confidence. PROTAC: ubiquitination databases record sites on it.
Gene: Protein-coding gene on chromosome 16 (1,678,256 to 1,702,859, forward strand). Ensembl gene ENSG00000206053.
Subcellular location: Cytoplasm; Nucleus
Subcellular location (Human Protein Atlas): Cytosol; Plasma membrane
Gene Ontology:
Molecular function: protein binding
Biological process: endocytosis involved in viral entry into host cell; regulation of calcium-mediated signaling
Cellular component: cytoplasm; cytosol; nucleus
Genetic constraint (gnomAD): Loss-of-function variants: 9 observed, 16.32 expected, observed/expected ratio (o/e) 0.55, 90% interval 0.33 to 0.96. The upper end of that interval is the gene's LOEUF score, 0.96, which puts it in group 4 of 6, group 1 being the genes least tolerant of losing a copy. Missense variants: 267 observed, 259.56 expected, observed/expected ratio (o/e) 1.03, 90% interval 0.93 to 1.14. Synonymous variants: 95 observed, 93.69 expected, observed/expected ratio (o/e) 1.01, 90% interval 0.86 to 1.2.
Homologues: Orthologues: chimpanzee JPT2 (99% identical), macaque JPT2 (94% identical), guinea pig JPT2 (84% identical), dog JPT2 (84% identical), pig JPT2 (82% identical), mouse Jpt2 (79% identical), mouse 1700049L16Rik (75% identical), rat Jpt2l1 (72% identical), tropical clawed frog jpt2 (53% identical), zebrafish jpt2 (44% identical).
Diseases named in the same sentence as JPT2 in open-access papers:
JPT2 is named in the same sentence as 9 diseases in open-access papers, as found by Europe PMC text mining. Sharing a sentence is not in itself a finding about the gene and the disease. The quoted sentences say what the papers report.
breast carcinoma (2 papers, 2022). "Hematological and neurological expressed 1 like (HN1L), also known as JPT2, or C16orf34, is a multifunctional oncogene that we and other groups have recently identified in lung cancer, hepatocellular carcinoma, and breast cancer." (PMID 36476988, 2022).
Miscarriage (1 paper, 2024). A pregnancy that ends at a stage in which the fetus is incapable of surviving on its own, defined as the spontaneous loss of a fetus before the 22th week of pregnancy. "Next, we verified the role of JNK signaling in JPT2 expression in mice with miscarriages." (PMID 38417123, 2024).
cancer (3 papers, 2022 to 2024). A tumor composed of atypical neoplastic, often pleomorphic cells that invade other tissues. "These proteins were unexpected candidates given that LSm12 is an RNA-binding protein and JPT2 is otherwise mechanistically orphaned (although linked to cancers)." (PMID 35959977, 2022). "It is germane that the NAADP-binding protein, JPT2, is implicated in cancer progression." (PMID 35959977, 2022).
JPT2 also shares sentences with these, for which no sentence is quoted: esophageal squamous cell carcinoma (2 papers); hepatocellular carcinoma (2); lung cancer (2); esophageal cancer (1); liver cancer (1); tumor (1).